TOP2B (DNA topoisomerase II beta)
Description:
Key decatenating enzyme that alters DNA topology by binding to two double-stranded DNA molecules, generating a double-stranded break in one of the strands, passing the intact strand through the broken strand, and religating the broken strand. Plays a role in B-cell differentiation.
Synonyms: top2beta; TOPIIB; BILU
Tractability: Small molecule: an approved drug acts on it; a structure with a bound ligand is known; a high-quality ligand is known; it has a high-quality binding pocket; it belongs to a druggable protein family. PROTAC: UniProt records ubiquitination sites on it; ubiquitination databases record sites on it; its protein half-life has been measured; a small molecule that binds it is known.
Target class: Isomerase; Enzyme
Gene: Protein-coding gene on chromosome 3 (25,597,978 to 25,664,973, reverse strand). Ensembl gene ENSG00000077097.
Subcellular location: Nucleus, nucleolus; Nucleus, nucleoplasm; Nucleus
Subcellular location (Human Protein Atlas): Nucleoplasm
Pathways (Reactome):
Metabolism of proteins: SUMOylation of DNA replication proteins
Gene Ontology:
Molecular function: chromatin binding; DNA topoisomerase type II (double strand cut, ATP-hydrolyzing) activity; protein binding; ATP binding; DNA binding; ribonucleoprotein complex binding
Biological process: B cell differentiation; DNA topological change; positive regulation of single stranded viral RNA replication via double stranded DNA intermediate; resolution of meiotic recombination intermediates; sister chromatid segregation; cellular response to ATP; cellular response to hydrogen peroxide; cellular senescence; DNA metabolic process; positive regulation of double-strand break repair via nonhomologous end joining
Cellular component: cytosol; heterochromatin; nucleolus; nucleoplasm; nucleus; chromosome; ribonucleoprotein complex
Genetic constraint (gnomAD): Loss-of-function variants: 32 observed, 131.19 expected, observed/expected ratio (o/e) 0.24, 90% interval 0.18 to 0.33. The upper end of that interval is the gene's LOEUF score, 0.33, which puts it in group 1 of 6, group 1 being the genes least tolerant of losing a copy. Missense variants: 1,212 observed, 1,619.9 expected, observed/expected ratio (o/e) 0.75, 90% interval 0.71 to 0.79. Synonymous variants: 557 observed, 554.54 expected, observed/expected ratio (o/e) 1, 90% interval 0.94 to 1.08.
Gene-disease validity (ClinGen):
ClinGen rates the evidence that TOP2B causes each of these diseases.
B-cell immunodeficiency, distal limb anomalies, and urogenital malformations (autosomal dominant): Moderate.
Homologues: Orthologues: chimpanzee TOP2B (99% identical), macaque TOP2B (99% identical), pig TOP2B (97% identical), dog TOP2B (96% identical), guinea pig TOP2B (96% identical), rabbit TOP2B (96% identical), mouse Top2b (96% identical), rat Top2b (95% identical), tropical clawed frog top2b (83% identical), zebrafish top2b (74% identical). Paralogues in human: TOP2A (66% identical).
Diseases named in the same sentence as TOP2B in open-access papers:
TOP2B is named in the same sentence as 78 diseases in open-access papers, as found by Europe PMC text mining. Sharing a sentence is not in itself a finding about the gene and the disease. The quoted sentences say what the papers report.
heart failure (16 papers, 2013 to 2026). Inability of the heart to pump blood at an adequate rate to meet tissue metabolic requirements. "By the cardiomyocyte-specific deletion of Top2β (encoding Top2β), progressive heart failure caused by DOX can be prevented." (PMID 37602332, 2023). "In these experiments, using a myoblast cell line from rat, the wild-type allele (427Ser) significantly reduced the expression of Top2b and the 427Leu allele that was associated with increased risk of heart failure showed only weak reduction of Top2b." (PMID 34575190, 2021). "Strong evidence has been gathered for the protective effect of DEX based on a Top2β-related mechanism in DOX-induced heart failure." (PMID 39769331, 2024). "This is important functional evidence because it is already known that doxorubicin binds to Top2b and that in mice, cardiomyocyte-specific deletion of Top2b is protective against doxorubicin-induced heart failure." (PMID 34575190, 2021). "In summary, the evidence in support of a pivotal role of Top2β in mediating doxorubicin-induced cardiotoxicity and heart failure is robust and convincing." (PMID 30792806, 2018). "Importantly, the cardiac-specific deletion of Top2β protected against the development of DOX-induced heart failure, showing that Top2β is a critical mediator of DOX-induced cardiotoxicity." (PMID 35163838, 2022). "Importantly, they also show that cardiomyocyte-specific deletion of Top2β protects mice from the development of doxorubicin-induced progressive heart failure, providing robust support for the view that doxorubicin-induced cardiotoxicity is mediated by Top2β in cardiomyocytes." (PMID 30792806, 2018). "We identify TOP2B upregulation as a key driver of cardiotoxicity and demonstrate that ASO therapy targeting TOP2B prevents heart failure and improves survival in preclinical models, providing a promising strategy to protect patients with cancer during chemotherapy." (PMID 42102394, 2026). "Mice with cardiomyocyte-specific deletion of the TOP2β do not develop DOX-induced heart failure, therefore, it is suggested that TOP2β plays a key role in DOX-mediated cardiotoxicity." (PMID 37711551, 2023). "In a mouse model of cardiomyocyte-specific deletion of Top2β gene, the lack of Top2β in heart cells was shown to protect mice from doxorubicin-induced heart cell damage and development of progressive heart failure." (PMID 30404148, 2018). "It prevents anthracycline-induced heart failure via TOP2B degradation in heart tissues rather than via iron chelation." (PMID 25406834, 2014). "Taken together, our data support a model of anthracycline-induced heart failure caused by TOP2B-mediated DSB and of its prevention by DRZ via TOP2B degradation rather than via iron chelation." (PMID 25406834, 2014). "Furthermore, cardiomyocyte-specific deletion of the Top2b gene protected mice from the development of progressive heart failure induced by repeated DOX treatment, suggesting that DOX-induced cardiotoxicity is primarily mediated by cardiomyocyte TOP2B." (PMID 24116135, 2013). "Thus, regardless of the many mechanisms through which DOX has cardiotoxic effects via Top2β, the two mentioned mechanisms via the DOX–Top2B–PGC pathway may be related to a cumulative effect, explaining the development of heart failure as an effect of late cardiotoxicity." (PMID 39769331, 2024).
cardiomyopathy (11 papers, 2015 to 2025). A disease of the heart muscle or myocardium proper. "Topoisomerase II beta (TOP2β) inhibition is also involved in the cardiomyopathy caused by anthracyclines." (PMID 33688366, 2021). "Cardiac-specific TOP2B deficiency rescued cardiomyocytes from doxorubicin-induced DNA double strand breaks, defective mitochondrial functions and increased ROS generation indicating that TOP2B is a critical mediator of doxorubicin-induced cardiomyopathy." (PMID 29464058, 2018). "Several calcium ion channels involved in cardiomyopathies are associated with TOP2B peaks including the voltage-dependent calcium channel CACNA1C, the sarcoplasmic reticulum calcium release channel RYR1, and the Na+/Ca+ exchanger and calcium anti-porter SLC8A1." (PMID 26459242, 2015). "If we reject free radical theory, as suggested by some authors, we need to explain the long, clinically silent period of the development of cardiomyopathy based on the Top2β mechanism." (PMID 39769331, 2024). "In contrast, inhibition of Top2β in cardiomyocytes is believed to be responsible for cardiomyopathy." (PMID 32961800, 2020). "Some reports have also demonstrated that embryonic fibroblasts lacking top2β were better protected against doxorubicin-induced cytotoxicity, and top2β deletion mice better prevented doxorubicin-induced cardiomyopathy." (PMID 26462155, 2015). "Furthermore, the deletion of Top2β protects mice from the development of DOX-induced cardiomyopathy." (PMID 39769331, 2024). "Evidence of the role of Top2β in ANT cardiomyopathy has been increasing." (PMID 39769331, 2024). "However, in subsequent studies, DEX was used to identify another important mechanism in DOX-induced cardiomyopathy that is related to topoisomerase 2β (Top2β)." (PMID 39769331, 2024). "Additionally, cardiomyocyte-specific deletion of Top2b ameliorated anthracycline-mediated cardiomyopathy." (PMID 33330654, 2020). "Knocking out Top2β in mice protects them from doxorubicin-induced cardiomyopathy, suggesting that depleting Top2β concurrently with doxorubicin treatment may be cardioprotective." (PMID 32961800, 2020). "This hypothesis has its origins within the guiding tenet that Top2β is required to initiate the entire phenotypic cascade of doxorubicin-induced cardiomyopathy." (PMID 30792806, 2018). "The current literature supports the hypothesis that the pathophysiology of anthracycline-induced cardiomyopathy is largely dependent on the targeting of Topoisomerase II beta (TOP2B) in cardiomyocytes, an increase in oxidative stress, and the disruption of mitochondrial homeostasis." (PMID 39002055, 2024). "Thus, the development of late cardiomyopathy can be explained based on mechanisms related to Top2β." (PMID 39769331, 2024). "We published previously that anthracyclines disrupt the catalytic activity of Top2b, resulting DNA double-stranded breaks, initiating a cascade of events, resulting in defective mitochondrial biogenesis and reactive oxygen species generation, thus precipitating cardiomyopathy." (PMID 33330654, 2020). "DEX, in addition to its iron ion chelation, affects Top2β, preventing the inhibition of this enzyme by DOX in cardiomyocytes, which results in a cytoprotective effect, decreasing the incidences of cardiomyopathy and congestive heart failure." (PMID 39769331, 2024). "Another protective mechanism of DEX in ANT cardiomyopathy was proposed, which is related to the prevention of the ANT inhibition of Top2β, antagonizing the formation of the enzyme cleavage complex and rapidly degrading Top2β." (PMID 39769331, 2024). "To date, no separate theory for the development of DOX-dependent cardiomyopathy based on the Top2β mechanism has been proposed." (PMID 39769331, 2024).
breast carcinoma (10 papers, 2014 to 2024). "Analysis of Top2A, Top2B, and cyclin D1 expression in 2254 human breast cancer samples showed cyclin D1, and TOP2A co-expression was associated with ERα+ tumors." (PMID 38191593, 2024). "We found that the downregulation of TOP2β levels upon VM-26 treatment was abrogated by MLN4924 in human breast cancer SK-BR3, MDA-MB231, and MCF7 cells." (PMID 32015321, 2020). "In this paper, a series of novel pyranoquinolinone based Schiff's bases were synthesized and evaluated for TOP2B inhibitory activity and cytotoxicity against breast cancer cell line (MCF-7)." (PMID 30110445, 2018). "Our study suggests that TOP2B is a valuable candidate that can be used to mitigate the cardiotoxicity induced by this combination therapy for HER2-positive breast cancer patients." (PMID 29464058, 2018). "This could be true specifically for breast cancer given the expression of TOP2B in >90% of breast cancer while TOP2A expression is limited in breast tumors as well as since TOP2B rather than TOP2A has been shown to be a better predictor for breast cancer survival in patients." (PMID 37927589, 2023). "More specifically, ATM knockdown via siRNA oligos in breast cancer SK-BR3 and MDA-MB231 cells or ATM knockout in mouse embryonic fibroblasts (MEFs) extended TOP2β protein half-life upon VM-26 treatment." (PMID 32015321, 2020). "Developing less toxic agents that target TOP2B may represent a therapeutic strategy to prevent ESR1 translocation events and deserves further study in the context of ER+ breast cancer." (PMID 31106278, 2019). "Quite the contrary, breast cancer survival can be predicted by TOP2B rather than TOP2A expression level." (PMID 25406834, 2014).
leukemia (9 papers, 2012 to 2025). A malignant (clonal) hematologic disorder, involving hematopoietic stem cells and characterized by the presence of primitive or atypical myeloid or lymphoid cells in the bone marrow and the blood. "This led to a model for the aetiology of TOP2 poison induced leukaemia where chromosome translocations are facilitated by co-localization of genes within common transcription factories, combined with TOP2B-mediated transcription-linked DNA breaks." (PMID 30223465, 2018). "While in principle either or both TOP2 isoforms could contribute to the induction of leukaemia-causing translocations via DNA cleavage at multiple loci followed by mis-repair, several lines of evidence point to TOP2B as the major contributor." (PMID 30223465, 2018). "TOP2B has also been implicated in the development of therapy related leukaemia." (PMID 30223465, 2018). "Our analysis of TCGA data showed that subsets of both breast and hematological cancer patients (the diseases of ongoing trials) also overexpress TOP2B, most strikingly in some leukemias." (PMID 34753908, 2021). "Recent studies have shown that TOP2β-DNA cleavage complexes have a preferential role in the generation of leukemia chromosomal break points." (PMID 32015321, 2020). "Daunorubicin, an FDA-approved chemotherapeutic drug indicated for treating leukemia, targets TOP2B, however, this agent is very toxic." (PMID 31106278, 2019).
prostate carcinoma (9 papers, 2012 to 2025). A carcinoma that arises from epithelial cells of the prostate gland. "In mammals, TOP2β-induced DSBs are necessary for the regulated transcription of neuronal early-response genes and for TOP2β mediated androgen-induced DNA rearrangements in prostate cancer." (PMID 28077781, 2017). "In prostate cancer cell lines, androgen signaling has been reported to induce recruitment of the AR-topoisomerase II beta (TOP2B) complex, which catalyzes DSBs at regulatory regions of AR target genes." (PMID 24244503, 2013). "Recently the male sex hormone androgen has been demonstrated to promote the recruitment of androgen receptor (AR) and topoisomerase II beta (TOP2B) to genomic breakpoints induced at androgen responsive genes including TMPRSS2: ERG fusion, the most common fusion detected in prostate cancer." (PMID 23272087, 2012).
autism (6 papers, 2015 to 2024). Persistent deficits in social interaction and communication and interaction as well as a markedly restricted repertoire of activity and interest as well as repetitive patterns of behavior. "Additionally, TOP2β is expressed in differentiation cells and neurons; the expression of long-transcripts linked to autism is facilitated by TOP2β." (PMID 32121304, 2020). "Recently, TOP2B has been implicated in the transcription of long genes in particular that play crucial roles in neural development and are susceptible to mutations contributing to neurodevelopmental conditions such as autism and schizophrenia." (PMID 26612825, 2016). "Given the role of TOP2B in neuronal gene expression, the H58Y substitution may perturb the gene expression patterns during neural development, which may eventually lead to autism." (PMID 36450898, 2022). "The role of TOP2B in neural development suggests it may be involved in neurodevelopmental disorders such as autism and schizophrenia." (PMID 26459242, 2015).
neuroblastoma (6 papers, 2016 to 2025). Neuroblastoma (NB) is the most common solid, extracranial childhood tumor. "For example, we recently reported that loss of TOP2B expression in SH-SY5Y neuroblastoma cells resulted in altered expression of many genes, and a reduced transcriptional response to retinoic acid (RA)." (PMID 40183884, 2025). "This view is reinforced by a recent study by Pan and colleagues, attributing the therapeutic activity of CX-5461 in high-risk neuroblastomas primarily to inhibition of Top2β." (PMID 39062087, 2024). "We used large-scale preclinical drug screening data to identify CX-5461 as exhibiting a selective and reproducible cytotoxic effect in high-risk neuroblastoma and we discovered that the primary target of CX-5461 at pharmacologically relevant concentrations is TOP2B." (PMID 34753908, 2021). "Using the retinoic acid responsive SH-SY5Y neuroblastoma cell line model, we had previously demonstrated many gene expression changes upon retinoic acid treatment and upon deletion of TOP2B." (PMID 40183884, 2025). "It was recently shown in a human neuroblastoma cell line model that genes downregulated in TOP2B null cells were enriched for very long genes (>200 kb) and for genes that are highly expressed in wild type cells." (PMID 37834253, 2023). "With the caveat that this TOP2B ChIP-seq data was derived from a non-neuroblastoma cell line, this is consistent with a requirement for localised TOP2B activity for correct expression of these genes." (PMID 35831557, 2022). "Since induction of neural differentiation markers BCL2 and NTRK2 was suppressed, we compared the expression of VIM, a characteristic marker of S-type neuroblastoma cells, in untreated wild-type and TOP2B null SH-SY5Y cells." (PMID 35831557, 2022). "This revealed CX-5461 treatment-induced TOP2cc formation, for both TOP2A and TOP2B, in all four neuroblastoma cell lines tested, again consistent with CX-5461 trapping TOP2 to DNA and behaving as a classical topoisomerase II poison." (PMID 34753908, 2021). "As was true for cell lines, TOP2B was more highly expressed in neuroblastoma tumors than other cancers." (PMID 34753908, 2021). "Together, these data are consistent with the high TOP2B expression in neuroblastoma cell lines being maintained in patient tumors." (PMID 34753908, 2021). "We first observed that although TOP2A and TOP2B were both overexpressed in neuroblastoma cell lines, the magnitude of TOP2B overexpression was substantially larger." (PMID 34753908, 2021). "We next explored the in vivo activity of TOP2B in primary tumors using neuroblastoma patient genomics data." (PMID 34753908, 2021). "Similarly, the normally large retinoic acid-stimulated induction of genes such as CYP26A1, CYP26B1, DHRS3 and CRABP2 is dramatically curtailed in TOP2B null neuroblastoma cells." (PMID 37834253, 2023). "Additionally, TOP2B expression was among the most highly negatively correlated genes with CX-5461 IC50 in GDSC neuroblastoma cell lines (r = −0.58, P = 1 × 10−3), and this was the 2nd highest negative correlation with TOP2B of all drugs screened." (PMID 34753908, 2021). "Overall, these genomics analyses of patient tumors suggest that high TOP2B activity is maintained and may be therapeutically relevant in a subset of neuroblastoma patients." (PMID 34753908, 2021). "Notably, Top2β is the primary oncogenic Top2 isoform in NMyc-driven cancers such as neuroblastoma, and this may explain the distinct mechanisms of action of CX-5461 in neuroblastomas and in lymphomas." (PMID 39062087, 2024). "SH-SY5Y is a neuroblastoma cell line that can be induced by RA to differentiate into adrenergic neuronal-like cells, making these cells a good model system to study the role of TOP2B in both RA-induced transcription and RA-induced differentiation of neuronal cells." (PMID 35831557, 2022).